CD4 (CD4 molecule)
Diseases named in the same sentence as CD4 in open-access papers (continued):
Sharing a sentence is not in itself a finding about the gene and the disease.
breast cancer (continued). "Breast cancers with a lot of TLSs also have more CD8+ T cells, which often take on tissue-resident or stem-like phenotypes, and a gene expression profile that favors a type 1 CD4+ helper T cell (Th1)/cytotoxic immune response." (PMID 41550427, 2025). "After vaccination, anti-HER-2 CD4 immune response was detected in blood and sentinel lymph nodes of breast cancer patients, and patients with DCIS exhibited much higher rate of pathologic complete response (pCR) than IBC patients (28.6% vs. 8.3%)." (PMID 40342927, 2025). "As one of the key immune cells in TME of HER2-positive breast cancer and TNBC, tumor-infiltrating lymphocytes (TILs), primarily consisting of CD8+ cytotoxic T cells, CD4+ helper T cells, regulatory T cells (Tregs) and NK cells, etc., indicates a better prognosis." (PMID 39188717, 2024). "Moreover, recent studies have shown decreased CD4+ and CD8+ T lymphocyte infiltration in DCIS and IDC breast cancer subtypes." (PMID 38533507, 2024). "Additionally, we investigated the possible mechanism by which CD4+ T cells activation was regulated by CCT2, which was derived from breast cancer cell exos." (PMID 39079960, 2024). "We next correlated tumor exosomal ENPP1 levels with CD8+ T cells and CD4+ T cells density across breast cancers and lung cancers, and found that total ENPP1 of breast cancers or lung cancers tissue inhibited the immune infiltration of CD8+ T cells and CD4+ T cells." (PMID 38498770, 2024). "In the CD4 low breast cancer cohort (n = 567), SCD expression data were not available for 59 patients (10.41%)." (PMID 39543650, 2024). "We found that the proportions of CD4+ T cells, CD8+ T cells and apCAFs were significantly higher in primary breast cancer, which demonstrates that the immune microenvironment may play an important role in the breast cancer metastasis process." (PMID 39157383, 2024). "In conclusion, we found the unique tumor immune composition resulting from the absence of Ing4 in mammary tumors, consisting of decreased CD4 CTLs indicative of an immune-evasive TME, correlating with increased penetrance (fitness for survival) and metastasis." (PMID 38968186, 2024). "In this study, we demonstrated that significantly reduced levels of CD3+T cells, CD4+T cells, CD8+T cells, DNT cells, NK cells, CD4+/CD8+ ratio, and LMR were detected in the peripheral blood of patients with breast cancer relative to patients with benign breast lesions." (PMID 38263363, 2024). "In patients with breast cancer, the count of CD19+ B cells in unvaccinated individuals was significantly higher than that in vaccinated patients, while CD4 and CD8 counts were significantly lower in unvaccinated breast cancer patients compared to vaccinated ones." (PMID 38826094, 2024). "In addition, studies have illustrated that CD4+ T‐cell ICOS expression increases in peripheral blood and tumor tissues of patients treated with anti‐CTLA4 for bladder cancer, breast cancer, and non‐small cell lung cancer." (PMID 38506253, 2024). "For example, in CD4+ T-cells, BCL9 for B-cell acute lymphoblastic leukemia (B-ALL); GAS7 and PRDM16 for Acute myelogenous leukemia (AML); ESR1 for breast cancer; and GRIN2A for colorectal, lung, and gastric carcinoma were differentially methylated between PWH and PWoH." (PMID 38466776, 2024). "However, the CD4, CD8, and NK cell counts were even higher in breast cancer patients than in liver cancer patients in spite of vaccination status, highlighting the disparity of immune cell profiles between the two cancer groups." (PMID 38826094, 2024). "Interestingly, since the expression of CCR4 is higher in Tregs than other CD4+ T cells, probably because of a FOXP3 responsive element on the CCR4 promoter, Tregs infiltration is favored in some tumors, e.g., in breast cancer." (PMID 39596815, 2024). "In the CD4 high breast cancer cohort (n = 533), SCD expression data were not available for 44 patients (8.26%)." (PMID 39543650, 2024).
breast cancer (continued). "Thus, the significant increase of infiltration of immune cells, particularly CD4+ and CD8+ T cells induced by TheraVacPlus, suggests added value with respect to immunotherapeutic efficacy of R848 in 4T1 breast cancer." (PMID 37190294, 2023). "Moreover, the application of cPLA2 inhibitors enhances the infiltration of activated and proliferating CD4+ and CD8+ T cells in TIME of aggressive breast cancer." (PMID 37965796, 2023). "In the non-invaded lymph nodes of breast cancer, the memory CD4+ T cells inhibits tumor progression by hindering lymph node metastasis." (PMID 36983615, 2023). "Moreover, CD molecules related to T cells, including CD4+ and CD8+ T cells were mentioned more often in pancreatic than in breast cancer studies." (PMID 37181043, 2023). "In a clinical study on breast cancer patients, MWA was found to significantly induce increased levels of ICOS+ activated CD4+ T cells and serum IFN-γ, indicating a multifaceted impact on the local and systemic levels beyond coagulation necrosis and protein degeneration." (PMID 37182153, 2023). "To further gain insight into the mechanistic basis of combination therapy in the 4T1 breast cancer model, we harvested draining lymph nodes and stained with fluorescent dye-conjugated anti-CD3, anti-CD4, anti-CD8, anti-CD44, and anti-CD62L antibodies for flow cytometry." (PMID 37190294, 2023). "Studies have examined whether CD4 + T cells alleviate CD8 + T cells exhaustion, and high infiltration levels of CD4 + T cells and CD8 + T cells predicted better survival for patients with breast cancer." (PMID 37600707, 2023). "Additionally, we also observed that the up-regulation of E2F8 was accompanied with higher enrichments of CD4+ T cells and CD8+ T cells in breast cancers." (PMID 36814821, 2023). "A ‘triculture’ setup of the PyMT-derived organoids, CD4+ T effector cells directly derived from PyMT mammary tumors and TAMs without exogenous stimulation revealed the M2-like TAM phenotype was promoted by higher IL-4 expression in CD4+ T cells." (PMID 36809334, 2023). "Intracellular cytokine production of IFN-γ and IL-2 upon PMA/lonomycin or T cell receptor (TCR) cross-linking stimulation was reduced in CD4+ and CD8+ T cells of breast cancer patients (9/19) compared to healthy donors’ (19/19) PBMCs, further indicating impaired function of these cells." (PMID 37741983, 2023). "Compared with that in patients with benign tumors, the proportion of CD4+Tn cells in patients with breast cancer decreased (mean: 27.9 vs. 33.5, P = 0.011), while the absolute number and proportion of CD4+CD57+T and CD4+PD-1+T cells significantly increased (P < 0.05)." (PMID 36925914, 2023). "Notably, cell cycle regulatory proteins including CD4/6 and RB1 have been found to have a significant impact on the regulation of breast cancer cell proliferation." (PMID 37885035, 2023). "CD4+T cells could increase the secretion of IL4, IL2 promoting breast cancer progression, and the mature dendritic cells induced the proliferation of CD4+T cells." (PMID 36644231, 2023). "Besides CXCL13 producing CD8+ T cells tumour infiltrating CD4+ T cells also display an enhanced capacity for CXCL13 production in lung cancer, breast cancer and ovarian cancer." (PMID 37520560, 2023). "Additionally, CD4+T cells and CD8+T cells play a crucial role in the anti-tumor response in various cancers, including colorectal cancer and breast cancer." (PMID 37881431, 2023). "Furthermore, the combination therapy of TEM and anti-PD-L1 antibodies enhanced anti-cancer immunity by increasing both the number and activity of CD4+ and CD8+ T cells in the tumor and draining lymph nodes (DLNs) of breast cancer-bearing immunocompetent mice." (PMID 36077620, 2022). "It has been reported that in lung, renal, prostate, and breast cancers, CD4+ T-cell density is a negative prognostic factor." (PMID 36253752, 2022).
breast cancer (continued). "CD4+ and CD8+ T cells as immunological parameters were well known to assist the activation of the antigen-presenting cells via cytokine secretion, which favored the prognosis of breast cancer." (PMID 35433455, 2022). "In addition, the number and activity of CD4+ and CD8+ T cells were increased in the tumors and DLNs of breast cancer-bearing immunocompetent mice by the combined administration of TEM and anti-PD-L1, thereby inducing anti-cancer immunity." (PMID 36077620, 2022). "By secreting CXCL12, CAFs attract conventional CD4+ T cell migration through its receptor-CXCR4 and promotes their differentiation into Foxp3+ regulatory T cells to create an immunosuppressive environment in human breast cancer." (PMID 35853880, 2022). "Breast cancer patients from The Cancer Genome Atlas (TCGA) databases with a higher ES score of the LAIT versus GC upregulated gene set in the CD8+ and CD4+ T cells exhibited prolonged overall survival compared to the patients with lower ES score of such gene set expression." (PMID 35808806, 2022). "Statistical parameters determined (absolute count, proportion, intensity and overall scores) indicated significant increase (p<0.05) in the number of CD4+ (T helper cells), CD8+ (cytotoxic T cells) and IL-2+ (activated T cells) in mammary tumor tissues of TM-F3 when compared to the TM group." (PMID 35972917, 2022). "Moreover, more significant percentages of CD4+ T lymphocytes expressing PD1 and CD39 were detected in breast cancer tissue than in peripheral blood of TNBC and higher than in healthy breast tissue." (PMID 35051220, 2022). "Furthermore, a previous study reported that naïve CD4 + T cells are recruited and converted to Treg cells by macrophages-derived CCL18 in breast cancer." (PMID 36221095, 2022). "By contrast, the good survival group (cluster 2 in METABRIC and cluster 1 in TCGA breast cancer) had the highest scores in memory resting CD4 T cells and resting mast cells, and the lowest scores in follicular helper T cells and M0 macrophages in both METABRIC and TCGA breast cancer studies." (PMID 35286348, 2022). "PECS II block was found to raise the numbers of CD3+, CD4+, and CD4+/CD8+ T cells in peripheral blood 3 and 24 h after breast cancer surgery in another study, implying that PECS II blockade can also improve cellular immune activity in patients undergoing surgery." (PMID 37786735, 2022). "The anti-cancer activity was assessed in histological preparations of breast organs, CD4+/CD8+ T cells from spleen organs, and several essential cytokines involved in breast cancer, such as IL-1, IL-6, TNF-α, IFN-γ, TGF-β, and IL-10, in the blood serum of mice." (PMID 35765486, 2022). "Thus, a novel antitumor mechanism driven by TSLP-stimulated CD4+ T cells and delivered by TNF-α and IFN-γ cytokines results in the senescence of advanced breast cancer cells." (PMID 36467403, 2022). "The CD3, CD4, and CD8 expression variation were also found in breast cancer patients." (PMID 35894707, 2022). "Therefore, the expression of ICRs on CD4, CD8, Vγ9Vδ2 (Vδ2), and Vδ1 T cells from the PBMCs of breast cancer patients was analyzed." (PMID 35880165, 2022). "There is also other evidence indicating that the majority of CD4+CD25+Foxp3+ Tregs are TNFR2+, and they expressed TNFR2 with the highest intensity in the TDLNs of breast cancer, up to 90.5% ± 11.3%, when compared with other CD4+ T cells, which highlights the importance of TNFR2 in Tregs." (PMID 35251045, 2022). "Furthermore, tumor-infiltrating immune cells (such as CD4+, CD8+, CD56+, and Foxp3+ cells) in E0771 and 4T1 breast cancers treated with SI-2 and in SRC-3 KD E0771 and 4T1 breast cancers were determined by immunohistochemistry." (PMID 36316775, 2022). "Previous studies have also shown that CD4+ T cells significantly inhibit tumor development, neutrophils, and DCs, and our study also revealed correlations of the NEK2 gene with several immune infiltration rate algorithms in breast cancer tissues." (PMID 34834441, 2021).
breast cancer (continued). "Univariate Cox regression analysis based on immune infiltration scores was performed, and the results were ranked to identify several immune cells in breast cancer that are the main protective factors, including Tfh, CD8 T, Tcm, MAIT, CD4 T, NK, Tgd and Th2 cells." (PMID 33986754, 2021). "The immune alterations observed in vitro were broadly recapitulated in our murine model of ER+ breast cancer where the total number of CD3+ cells and the proportion of CD4+ T cells was higher in letrozole-treated tumours when compared to vehicle-treated tumours." (PMID 34602068, 2021). "Analysis of mammary tumors exhibited no significant changes in total immune cells, macrophages, myeloid-derived suppressor cells (MDSCs), and total T cells (including CD4 and CD8 T cells) present in the tumors." (PMID 34638488, 2021). "However, both CD4 and CD8 T cells increase and participate in immune response, showing an obvious dynamic trend in the development of breast cancer." (PMID 34659411, 2021). "Since NKG2D is also expressed on NKT cells, CD8+ T cells, γδ T cells, and some activated CD4+ T cells, fusion protein MICA-G129R may also attract and activate these cells to fight against breast cancer." (PMID 34077462, 2021). "In the present study, we have shown that blockage of CTLA-4 receptor on lymphocytes and concomitant reduction of CD4+CTLA-4+ and CD8+PD-1+ cells seem to be a crucial element in inhibition of MDA-MB-231 breast cancer cell proliferation and their arrest in the G1-phase." (PMID 34440813, 2021). "The higher percentages of CD3 and CD8 in primary sites and CD4 in the peritumoral primary sites were found than that in normal breast cancer." (PMID 34858823, 2021). "In breast cancer, TSLP produced by cancer cells activates DC and results in Th2 inflammation, which promotes tumorigenesis; whereas in mouse, TSLP can induce immunosuppressive factors by activating CD4+ T cells that promote Th2-mediated immune responses." (PMID 33652749, 2021). "The ratio of CD4/CD8 is correlated to clinical aspects and could be used as prognostic factor for breast cancer, where a higher CD4/CD8 ratio in the INT group correlated to mammary tumor progression." (PMID 34164110, 2021). "In addition, the distribution of circulating CD4 + CD25 + FOXP3+ Treg lymphocytes and CD19 + CD24 + CD38 + B lymphocytes significantly increased in breast cancer patients compared with healthy controls using blood samples." (PMID 33726701, 2021). "CD8 positive T cells, resting CD4 positive memory T cell, CD4 positive naive T cells, and gamma delta T cells showed no statistical difference between normal breast tissue and breast cancer tissue." (PMID 34572478, 2021). "Compared to the tumors that underwent a surgical resection alone, we observed a significant increase in dendritic cells, macrophages and B lymphocytes, as well as CD3, CD4, CD8, CD4/CD8, NK cells and activated cytotoxic T lymphocytes (CTLs) in HIFU-treated breast cancer." (PMID 34943854, 2021). "In summary, low intensity (18 Vpp) and intermediate frequency (100 kHz) non-contact electric fields exposure showed inhibition of mammary tumor growth in rats by inducing CD8+ T cells that lead to tumor cell death supported by a decreased CD4/CD8 ratio." (PMID 34164110, 2021). "The CD4+T cells obtained from DLNs of tumor bearing CD4+NFAT5-KO mice following three stimulations with high salt did demonstrate a cytotoxicity of just 11 ± 4% (wild-type: 67 ± 9%; p < 0.05) on py230 breast cancer cells (E:T ratio 20:1)." (PMID 33918403, 2021). "In recent years, research has showed that the absolute number or subset of CD4+CD25+Tregs increases in peripheral blood, lymph node, and tumor tissue of patients with breast cancer and closely related to the pathological type of breast cancer and progress." (PMID 33029539, 2020).
breast cancer (continued). "We designed our study to investigate the effects of iron isomaltoside, a clinically approved intravenous iron compound, on the course of disease, therapeutic efficacy of anti-cancer immunotherapies and anti-tumor response of CD4+ and CD8+ tumor infiltrating T cells in the E0771 breast cancer model." (PMID 33344239, 2020). "For instance, CD147 could promote breast cancer cell metastasis and invasion by contribution of MMP2, MMP9, and VEGF expression, and CD147-mediated chemotaxis of CD4+CD161+ T cells may contribute to local inflammation in rheumatoid arthritis." (PMID 33015178, 2020). "This was due to secretion by CD4+ T cells of pro-tumor Th2 cytokines (i.e., mainly IL-10 and IL-13), possibly with activation of CD4+ NKT and myeloid suppressive cells, and tumor-derived CCL17 that in turn recruited Tregs already described to have a pro-metastatic role in breast cancer." (PMID 33042121, 2020). "Future experiments could investigate the involvement of the Fc-region of CD4 + T-cells and whether co-precipitation experiments can identify interaction between CD4 + T-cells and HER2 + breast cancer cells treated with trastuzumab." (PMID 33292267, 2020). "Similar results with CD4+ T-cell depletion and reduced therapeutic response were observed when a group used a stimulator of interferon genes (STING) agonist alongside OX40R agonist with PD-L1 blockade in a NT2.5 breast cancer model." (PMID 32937885, 2020). "The quantities of intratumoral and stromal TIL subsets (CD8+, CD4+, and FOXP3+ TILs) in pre- and post-PST breast cancer samples, as well as changes between them, were analyzed along with their correlations with clinicopathologic features and outcome of patients." (PMID 32401825, 2020). "Similar results were also obtained in a mouse model of breast cancer in which transplanted human MSCs significantly reduced CD3+ NKp46 NKT-like cells, increased CD4+ Foxp3 T cells and IL-10 expressing CD4+ cells, increased serum Th2 cytokines, and decreased serum Th1 cytokines." (PMID 32637408, 2020). "CD4+ Tem, CD8+ Tcm, CD8+ T-cells, CD8+ naive T-cells, and B cells were positive prognostic factors but CD4+ naive T-cells were negative prognostic factors for breast cancer patients." (PMID 32728493, 2020). "The dynamics and roles of CD4+, CD8+ and Tregs cells in the pathogenesis of breast cancer remain unclear." (PMID 33312693, 2020). "Fluorescently-labeled breast cancer cells (BT474, SKBR3, MDA-MB-453, and MDA-MB-231) were co-cultured with CD4 + T-cells (Jurkat cell line) and longitudinally imaged to quantify cancer cell viability when treated with or without trastuzumab (10, 25, 50 and 100 μg/mL)." (PMID 33292267, 2020). "CD8+ naive T cells versus CD4+ naive T cells were favorable prognostic factors for the overall survival of breast cancer patients, suggesting that not all T cells were protective." (PMID 32728493, 2020). "Evidence also suggests that CD4 and CD8 T cells can act as biomarkers and therapeutic targets for breast cancer treatment, which is in keeping with our finding that higher risk scores based on the eight-IRG signature were associated with higher levels of CD8 and resting CD4 memory T cells." (PMID 32756008, 2020). "Since breast cancer cell lines and tissues appear to express HERVs, and the local microenvironment of breast cancer contains potentially HIV infected-CD4+ cells, there is the possibility of direct or indirect interaction between HERVs dysregulated by HIV and HERVs dysregulated in breast cancer." (PMID 33194615, 2020). "In addition, after radiation therapy for mammary carcinoma, the increase of lymphocytes found in patients’ BALF mainly consisted of activated cluster of differentiated CD4 + cells migrating from the irradiated lung to the contralateral one7,8." (PMID 33199774, 2020).